CD4 (CD4 molecule)
Diseases named in the same sentence as CD4 in open-access papers (continued):
Sharing a sentence is not in itself a finding about the gene and the disease.
influenza (continued). "CD8+ and CD4+ T cells provide cell-mediated cross-protection against multiple influenza strains by recognising epitopes bound as peptides to human leukocyte antigen (HLA) class I and -II molecules respectively." (PMID 35051231, 2022). "Immune stability was significantly lower in immunotypes that contained aging‐associated immune subsets and correlated with a circulating CD38 + CD4+ T follicular helper cell increase 7 days after influenza vaccination." (PMID 36081314, 2022). "In this study, we investigated the SARS-CoV-2-specific CD4+ T cell phenotype in comparison with H1N1 influenza-specific CD4+ T cells." (PMID 36146622, 2022). "Using this information, we have analyzed the localization of infection-elicited virus-specific CD4 T cells in secondary lymphoid tissues and lung, and we have examined the distribution of influenza B-specific CD4 T cells in lung sub-compartments." (PMID 35215193, 2022). "Strikingly, significantly elevated numbers of monoclonal OVA specific Tfh cells were generated from adoptively transferred naïve CD4+ OT-II T cells inside MedLNs of influenza infected ICAM-1/2-/- mice." (PMID 36895258, 2022). "We analyzed activated (CD38+) circulating CD4+ T follicular cells pre‐ and post‐vaccination which were previously shown to be a good predictor of influenza vaccination response." (PMID 36081314, 2022). "The humoral immune system produces antibodies against different influenza antigens, whilst cell mediated immunity includes DC, CD4+ helper T cells and CD8 + cytotoxic T cells." (PMID 36479289, 2022). "Utilizing MHC Class II tetramers, we also determined the influenza-specific lung tissue resident Treg and CD4+ conventional cell populations displayed distinct kinetics in response to secondary infection." (PMID 36159872, 2022). "Similar increases in mitochondrial oxidation were seen in CD4+ T cells isolated from obese mice following influenza reinfection." (PMID 36275776, 2022). "While CD4+ Trm are an under-appreciated population, multiple studies have found them sufficient for protection in a mouse model of influenza challenge." (PMID 36275668, 2022). "It has been proposed that alternative pathways of antigen processing in infected APCs, rather than virion or infected cell uptake, is the primary driver of CD4+ T cell response to influenza infection." (PMID 35051231, 2022). "Specifically, in old mice, it has been demonstrated that senolytic drugs can impact CD4+ T cells, most likely by modulating the microenvironment, which can then positively influence T cell differentiation during the response to influenza infection." (PMID 36077216, 2022). "Although primarily explored for CD8 T cells, recent studies by our group and others have shown that influenza-specific CD4 T cells home to lung tissue to deliver anti-viral effector function." (PMID 35215193, 2022). "In a study on lung airways of influenza infected mice, a plethora of CD4+ TRM cells were detected that were characterised by expression of CD69 and CD11a." (PMID 36211412, 2022). "We have also found that influenza-specific, cytokine-producing CD4 T cells are recovered from the BAL in IBV-infected mice (data not shown)." (PMID 35215193, 2022). "Our results showed that immune stability correlated with a circulating CD38+ CD4+ T follicular cell increase 7 days after influenza vaccination." (PMID 36081314, 2022). "Specifically, influenza antigens conjugated to both 3 μm and to 500 nm particles induced higher levels of the pro-inflammatory cytokines IFNγ and TNFα in CD4+ T cells than the unconjugated particles." (PMID 35890185, 2022). "In 2006, a study demonstrated that after vaccination with a TIV, influenza-specific IFN-γ+ CD4+ and CD8+ T-cells were significantly increased in children aged 6 months to 4 years, but not in children of 5 to 9 years old nor in adults." (PMID 36052083, 2022).
influenza (continued). "The strong interconnection between early influenza-specific CD4 T cell activation and the emergence of a Tfh signature on day 4 raises the question whether these signatures are associated with vaccine-elicited antibody titers as has recently been shown on the bulk CD4 level." (PMID 34795301, 2021). "In animal studies, it has been shown that the activated influenza-specific CD4 T cells were able to upregulate Bcl6 and become “TFH-committed” cells in the aged hosts." (PMID 34158111, 2021). "The generation of protective humoral immunity is supported by CD4+ helper T cells, which, like neutralising antibodies, are correlates of protection for influenza infection." (PMID 34726156, 2021). "CD4 T follicular helper cells can provide cognate help to influenza-specific B cells and CD8 T cells, including those that reside directly in the respiratory tract." (PMID 34970279, 2021). "We analyzed CXCR5+PD-1high expression on total CD4+ T cells in a small subset of influenza+ patients and also found very low levels in the blood at both acute and follow-up timepoints (0-0.2%)." (PMID 33976217, 2021). "Adaptive transfer of effector CD4+ T cells isolated from mice infected with influenza demonstrated enhanced survival of recipient mice challenged with the virus." (PMID 35222350, 2021). "In this lethal influenza challenge, the transfer of serum or sorted CD4+T cells from OVX836-immunized mice into recipient mice did not confer significant protection." (PMID 34177921, 2021). "During influenza infection, CD4 T cell help occurs at the priming phase of T cell responses, which is critical for the development of CD8 TRM cells in the lung." (PMID 34572004, 2021). "Female mice show greater CD4+ T and B-cell proliferation and developed more robust neutralizing antibody and total IgG responses compared to male mice following influenza vaccination." (PMID 34372607, 2021). "The plant-based VLP influenza vaccine was able to induce robust antibody responses and antigen-specific CD4+ T cells." (PMID 34579269, 2021). "Mass cytometry has also been used to identify novel influenza vaccine-specific CD4+ T-cell subsets in humans." (PMID 34205932, 2021). "For example, in H1N1-infected BALB/c mice, a slightly higher proportion of influenza-specific CD4 T cells were found to target the HA antigen than NA." (PMID 34684240, 2021). "Using pMHCII-tetramer technology, we analyzed HA118-132- and HA306-318-specific CD4 T cells ex vivo in HLA-DRB1*01:01-positive individuals who received influenza vaccination in 2016/2017, 2018/2019, 2019/2020, and/or 2020/2021." (PMID 34795301, 2021). "The broad specificity of CD4+ T cells results from their heterozygosity at HLA loci, but most circulating cells are reactive to the conserved influenza matrix protein." (PMID 34207924, 2021). "We used the standard specifications of the model to simulate the CD4+ T cell response to influenza infection." (PMID 34343169, 2021). "Adoptive transfer of CD4 T cells isolated from the lung of mice boosted with the influenza NP-nanoparticle vaccine was sufficient to mediate protection from a lethal influenza virus challenge." (PMID 34970279, 2021). "The major trends in the population dynamics of CD4+ T cells during influenza infection, including the time delay of the target-organ dynamics relative to the lymph-node dynamics, were conserved as we varied this parameter." (PMID 34343169, 2021). "It has been further demonstrated in mice that inhibition of mTOR by rapamycin enhances cross-strain protection against influenza in a CD4+ T cell- and B cell-dependent manner." (PMID 36845567, 2021). "Collectively, these data demonstrate that the expansion dynamics of influenza-specific CD4 T cells are heterogeneous among vaccinees but appear to be linked to the individual’s vaccination history." (PMID 34795301, 2021).
influenza (continued). "Single-cell RNA sequencing shows that transcriptional programs of both CD14+ monocytes and CD4+ T cells were considerably altered by the seasonal influenza vaccination." (PMID 34695164, 2021). "A subset of CD4 T resident helper cells have been identified in the influenza infected lung that can provide help for lung localized CD8 Trm and B cell resident memory (Brm) responses." (PMID 34970279, 2021). "A previous in silico study identified that the pdmH1N1 HA protein carries more promiscuous epitopes and are cross-reactive to the pre-existing influenza-specific CD4+ T cells than other seasonal flu strains." (PMID 34679115, 2021). "Numbers of influenza-specific CD8+ or CD4+ T cells increase early in disease and retain an activated phenotype during patient recovery." (PMID 33976217, 2021). "CD4+ TNF-α production upon influenza stimulation was observed in both TIV and LAIV recipients, regardless of colonization status, but not in unvaccinated individuals." (PMID 33497364, 2021). "Another study showed influenza vaccination to activate CD4+ and Th1–type cells, which induced the secretion of Th1-type cytokines and promoted T cell immunity." (PMID 34721391, 2021). "In a recent study, recombinant HA vaccine demonstrated superior HA-specific both antibody and CD4+ T cell responses in adult human cohorts when compared with inactivated influenza vaccine." (PMID 35222350, 2021). "Previous randomized trials have measured the CMI response to influenza vaccination in older adults according to changes in IFNγ+, CD4+, or CD8+ T cell frequencies." (PMID 35128529, 2021). "The best proofs for this crucial role are that IL-17 neutralization impaired the mucosal protective immunity induced by nasal vaccination and that CD4+ cells secreting IL-17 were found after influenza infection." (PMID 33717074, 2021). "Overall, our analysis demonstrates that seasonal influenza vaccination recalls antigen-specific memory CD4+ T cells and promotes their differentiation into Tfh cells with similarity to lymph node GC Tfh cells." (PMID 34726156, 2021). "Vaccine strategies that leverage the effector functions of CD4+ T cells have been proposed as a potential step towards universal influenza vaccines." (PMID 34207924, 2021). "We validated the platform’s ability to predict CD4+ T cells’ emergent behaviors by reproducing their differentiation patterns, metabolic regulation, and population dynamics in response to influenza infection." (PMID 34343169, 2021). "Prior studies from the Swain laboratory suggest that robust influenza-specific memory CD4+ T cell formation requires two cognate TCR-MHCII encounters: the first priming interaction in the lymph node, and a second around days 5–7 post-infection." (PMID 34183650, 2021). "Both influenza-specific CD4 and CD8 T cells make critical contributions to anti-viral immune responses in the lung." (PMID 34970279, 2021). "Studies using influenza-infected mice have shown involvement of CD4+ T populations in perforin/granzyme-mediated cytolytic activity." (PMID 35222350, 2021). "Studies have shown that adoptive transfer of in vitro-derived memory CD4+ T cells into NK-depleted BALB/c mice curtailed influenza-induced morbidity via reduced NK-driven inflammation." (PMID 33903648, 2021). "The majority of Tet+ cTfh cells expressed CXCR3, consistent with the ‘Th1’ skew in the total CD4+ T cell and cTfh cell response to influenza vaccination." (PMID 34726156, 2021). "In previous studies, ICOS and CD38 upregulation was associated with the presence of a cTfh cell phenotype on bulk CD4 T cells after influenza vaccination." (PMID 34795301, 2021). "The mean overall influenza-specific CD4 T cell reactivity at baseline was 1414 ± 287 (numbers of responding CD4 cells per million of total CD4 cells)." (PMID 33922875, 2021). "The influenza vaccine response is mediated mostly by the humoral immune system (B-cells) aided by CD4 T-cells." (PMID 34842142, 2021).
influenza (continued). "We showed that intranasal vaccination with an influenza NP-nanoparticle vaccine elicited a polyfunctional subset of CD4 T cells that persisted long-term in the lung." (PMID 34970279, 2021). "There was a higher number of lung infiltrating CD4+ T cells after influenza infection of Siglec-H ko mice compared to wt mice and among these a higher IL-4 production." (PMID 34497606, 2021). "We isolated CD4+ T cells from the spleens of influenza or ECTV infected mice, co-cultured with BMDCs presenting MHCII peptides derived from either direct presentation or indirect presentation and measured T cell activation using an IFNγ ELISpot." (PMID 32745153, 2020). "Because the response to influenza M1 and NP, correlates with protection in both CD4 and CD8 T cells, these internal proteins will be a necessary component of new vaccines for older adults." (PMID 32399058, 2020). "Natural influenza infection triggers a significant increase in CD4+ T-cell responses in SOT patients." (PMID 32572168, 2020). "We found little expression of both CD25 and CCR6 on the influenza-specific as well as the general CD4 population, while such phenotypes were detected in α-enolase- and CILP/fibrinogen-specific T cells." (PMID 32423478, 2020). "In this study, after being cocultured with BDCA3+ (CD141+) DCs stimulated by live attenuated influenza vaccine, naïve CD4+ T cells differentiated into both Th1 and Th2 cells." (PMID 32655564, 2020). "Valkenburg and coworkers reported that influenza-specific CD4+ and CD8+ effector memory T cells produced anti-viral cytokines and these had a protective effect." (PMID 32012159, 2020). "Numerically, influenza infection significantly increased the number of CD4+ T cell in the BAL and lung." (PMID 33373420, 2020). "In three successive seasons (2015–2016, 2016–2017 and 2017–2018), subjects were enrolled in a vaccination study to evaluate both their CD4 T-cell and B-cell responses to influenza vaccination." (PMID 32884842, 2020). "In this study, we performed a comprehensive study of the human CD4 T-cell response to vaccination with these three distinct types of licensed influenza vaccines." (PMID 32884842, 2020). "The poorer disease outcome in MKP-1 KO mice was associated with reduced influenza-specific CD8+ T-cells in the lungs and reduced expression of IFNγ by both antigen-specific CD4+ and CD8+ T-cells compared to WT." (PMID 32709018, 2020). "Similar to this study, a study in the United States from 2010 to 20119 recorded a higher prevalence of influenza in patients with a CD4 count over 200 cells/mm3 than those with less than 200 cells/mm3." (PMID 33392051, 2020). "In these studies, the reduced efficacy was due to lower CXCR3 expression on the CD4+ T cells, which led to reduced accumulation of these cells in the influenza infected lung." (PMID 33373420, 2020). "It has been shown that older adults exhibit lower T cell responses to influenza compared to young controls and that preexisting CD4+ T cells against conserved internal influenza proteins are important for limiting virus replication and disease severity." (PMID 33178213, 2020). "In regards to CD4+ T cell responses, Th1 polarized influenza specific CD4+ T cells can transfer immunity to a naïve host, while Th2 polarized cells offer no protection, highlighting the need for the induction of proper immunological responses." (PMID 33373420, 2020). "One day prior to viral challenge, we found that CD8α ALN-1 promoted both CD8+ and CD4+ T cell responses against epitopes of influenza’s NP." (PMID 32714571, 2020). "Tregs, typically characterized by their IL-10 secretion, inhibit the function of influenza-specific CD4+ and CD8+ T cells." (PMID 32974217, 2020). "In this study, we report the identification of influenza H1-HA peptides recognized by naive and memory CD4+ T cells in individuals with different HLA haplotypes." (PMID 32644114, 2020).
influenza (continued). "It is known that live influenza vaccines can induce protection by induction of mucosal IgA after local application, and CD4+ and CD8+ T cell responses." (PMID 32435514, 2020). "HLA-DR1 transgenic mice have also been used to model human influenza-specific CD4+ T cell responses and broadly target both surface and internal proteins." (PMID 31815739, 2020). "CD4 TRM cells are retained in the lungs of mice following influenza challenge and traffic back to the lungs of naïve mice following adoptive transfer." (PMID 33096737, 2020). "CD8+ T cells produce IL-10 in response to IFNAR signaling, IL-27, and CD4+ T cell-derived IL-2 during influenza infection in mice." (PMID 32974217, 2020). "We isolated splenic CD4+ T cells from mice infected with PR8 influenza as a source of activated T cells for analysis of superantigen-mediated stimulation." (PMID 32745153, 2020). "We report that LAIV induced early (3–7 days post-vaccination) activation of tonsillar follicles and influenza-specific TFH-cell (CXCR5+CD57+CD4+ T cell) responses in children, and to a lesser extent in adults." (PMID 31250024, 2020). "Of note, among influenza- and citrulline-specific cells as well as in the general CD4 population around half of the CXCR3+ cells also expressed CXCR5 and to a lesser extent CCR6 (data not shown)." (PMID 32423478, 2020). "Due to repeated confrontation by humans to influenza via vaccination and infection, most individuals have circulating memory CD4 T cells, B cells and antibodies to these components." (PMID 32884842, 2020). "Using DRP, we were able to identify two relevant CD4+ T cell clusters from the CyTOF data, one of which appears to be a pre-existing influenza virus–specific cluster, and the other was an influenza vaccine-responsive cluster." (PMID 33310880, 2020). "Polyfunctional influenza-specific CD4+ cells have been shown to be functionally superior, as shown by increased degranulation and higher production of CD40L and cytokine per cell." (PMID 32572168, 2020). "Phenotypically immature NK cells and CD4+ T cells are the predominant cytokine producing subsets in influenza infection." (PMID 32974217, 2020). "As expected, infection with influenza resulted in the increase in CD44hi CD4+ and CD8+ T cells in all tissues assessed, except for the spleen, as compared to the mock infected animals." (PMID 33373420, 2020). "The hierarchy of responses for CD4 T-cell reactivity to the influenza HA-B protein was less striking among the vaccines, although still statistically significant." (PMID 32884842, 2020). "A study investigating T-cell responses after influenza vaccination reported short-lived CD4+ T cell responses when PBMCs were stimulated with live (attenuated) virus strains." (PMID 32824111, 2020). "First, the antigen used for stimulation was calibrated on HA concentration, which is known to predominantly stimulate CD4+ responses whereas internal influenza proteins such as M1 and NP predominantly stimulate CD8+ responses." (PMID 32572168, 2020). "Although in influenza-infected mice, expression of CCL17 and CCL22 by airway epithelial cells is associated with imprinting of CCR4+CD4+ T cells by lung dendritic cells, our findings suggest that this does not occur with human RSV." (PMID 31815739, 2020). "Memory CD4+ T cells are required for long-lived immunity and are induced by vaccination strategies, including against malaria and influenza." (PMID 32802896, 2020). "Live influenza vaccines are purposive tools, inducing CD4 and CD8 responses similar to natural infection." (PMID 32230902, 2020). "In this study, we focused on CD4+ T cells, whose role is not completely understood in the context of influenza vaccination." (PMID 33310880, 2020). "identify several influenza epitopes from internal proteins and use them to explore the biochemical features that underpin CD4+ T cell responses to influenza." (PMID 32668259, 2020).